CD4 (CD4 molecule)
Diseases named in the same sentence as CD4 in open-access papers (continued):
Sharing a sentence is not in itself a finding about the gene and the disease.
infection (continued). "Opportunistic infections usually occur when CD4 cell count falls below 200 cells/microL." (PMID 39958093, 2025). "In mice, HIF2α activation in CD4+ T cells promoted intestinal Th2 cell accumulation in the absence of infection, and HIF2α-deficiency impaired CD4+ T cell-mediated host immunity to intestinal helminth infection." (PMID 39868305, 2025). "Thus, our data reveal a novel mechanism employed by HCMV to circumvent the recognition by CD4 + T cells during different stages of infection." (PMID 40608405, 2025). "It was hypothesized that this is due to infection of different cell types, namely CD4+ T cells and macrophages." (PMID 41467837, 2025). "Notably, M. tuberculosis-infected mice that received the LXR agonist on day 18 post-infection showed similar numbers of neutrophils and increased numbers of CD4 T cells, as compared to control mice." (PMID 41477004, 2025). "Therefore, the increased number of Meq+ CD4+ T cells in the rRB-1B_Meq-infected group at the late phase of infection implied the proliferation of MDV-transformed cells." (PMID 41013577, 2025). "In this study, the authors emphasized the limited development of polyfunctional T cells with the capacity to secrete multiple effector cytokines and increased numbers of “dysfunctional” CD4 T cells with an exhausted transcriptional signature at later time points after infection." (PMID 40815083, 2025). "However, we did see partial restoration of the “infection score—genes up with infection” in the naïve CD4 and Treg clusters of the MycTg and iMycTg-E mice." (PMID 40720380, 2025). "Uptake of HIV-1 particles through DC-SIGN leads to lysosomal degradation for MHC class I and II antigen presentation but can also “store” HIV-1 in multivesicular bodies or invaginations which can result in highly efficient trans-infection from DCs to CD4 + T cells." (PMID 40408432, 2025). "It would be of interest to further investigate why some, but not all, develop more pronounced CNS engagement by HIV and what factors besides duration of infection and CD4+ T-cell depletion affect the vulnerability of the CNS, for example virus tropism and host factors." (PMID 41120653, 2025). "However, after a brief increase during the effector stage of each infection, the number of total CD4 and CD8 T cells in the blood remained constant in all three groups." (PMID 40163479, 2025). "The mature virions are released and can infect other CD4+ cells, continuing the infection cycle." (PMID 40699766, 2025). "Furthermore, the expression of MICA/B on CD4+ T cells generally increased with the duration of infection, with a more pronounced elevation observed in the IR group." (PMID 40061947, 2025). "For example, the protective window of CD4+ T cells in craniotomy infection was observed during acute intervals, and brain CD4+ T cell infiltrates were highly activated during the first 2 weeks of S. aureus craniotomy infection in WT animals based on characteristic surface marker and Ki67 expression." (PMID 39989461, 2025). "Conversely, the number of CD4+ T lymphocytes gradually increased as the infection progressed." (PMID 40170749, 2025). "CD4 + T cells, as the main target for infection in the blood and the lymphoid system, may contribute to neuroinvasion of HIV/SIV, whereas CD8 + T cells, known to mediate antiviral functions, are more likely to promote neuroinflammation and neuropathogenesis." (PMID 40386405, 2025). "CD4+ T cell infection was quantified via p24 staining and flow cytometry." (PMID 40130873, 2025). "However, the present study indicated that prior infection with swIAV increased the presence of CD4 and perforin expressing lymphocytes in the lungs during PRRSV infection, potentially contributing to a more pronounced immune response against PRRSV." (PMID 40484956, 2025).
infection (continued). "Furthermore, exposure to antigen leads to an increase in the number of activated CD4+ T cells, which can enhance infection leading to an increased opportunity for the eventual entrance into the persistent proviral pool." (PMID 39723838, 2025). "Our initial suspicion that Themis might modulate CD4+ T cell function during chronic LCMV C13 infection was based on our previous finding that CD4+ T cell depletion in infected cKO mice reduced their mortality to 60%." (PMID 40777021, 2025). "Positivity for recent infection allows for discriminating cases diagnosed early after seroconversion that may be misdiagnosed as late diagnoses due to a low CD4 count." (PMID 41011735, 2025). "Also, the cellular environment generated after macrophage infection with lab-adapted or T/F HIV strains can enhance the infection of resting CD4+ T cells and can even skew the differentiation of activated CD4+ T cells into more permissive profiles." (PMID 40130873, 2025). "It is hypothesized that, over millennia, these genes accumulated variants enabling them to present a wider diversity of pathogen-derived peptides, thereby activating larger numbers of CD4+ T cells to defend the host against infection." (PMID 41425584, 2025). "Cytokine stimulation alone is sufficient to evoke an IFN‐γ response in CD4 TIA cells generated in vitro as well as isolated from various murine infection models or human PBMCs, thus revealing a broad adoption of innate‐acting capability by activated or memory CD4 T cells." (PMID 40923840, 2025). "A previous study has demonstrated that there is a significant reduction in CD4+CD8+ double-positive T cells in the peripheral blood at 3 days post infection (dpi), and further studies by other researchers found significant reductions in monocytes, B cells, and T cells in peripheral blood at 7 dpi." (PMID 40143222, 2025). "Additionally, children with inapparent infections had a higher frequency of preexisting Temra T cells in DENV-specific CD4+ and CD8+ T cells." (PMID 39989460, 2025). "To study this issue, we used an in vitro primary human CD4 + T cell infection model developed in our laboratory to identify HIV-1 integration sites that might influence cell proliferation or survival." (PMID 40627772, 2025). "Notably, the frequency of AIM+ CD4 T cells is reduced during TB treatment, which suggests a response to the declining antigenic stimulation and immune activation as the infection resolves." (PMID 40799590, 2025). "Furthermore, if there are sufficient preexisting, suppressive Tr1 cells to adequately influence immune responses and clinical outcomes to a new infection, it would be expected that CD4+ T cell expansion would be strongly suppressed." (PMID 41000872, 2025). "Clinical characteristics of the FRESH study participants including the number of days post first observed plasma viraemia for the sample analysed for this study, the stages of early infection when the blood samples were collected, viral load and CD4 T-cell count at the time of sample collection." (PMID 40549817, 2025). "However, a limitation for the development of a calnexin-specific antifungal vaccine is the low precursor frequency of naive endogenous CD4+ T cells and the modest expansion and protective efficacy after vaccination and infection." (PMID 41061037, 2025). "No clear differences in the changes in relative abundance during infection were observed between mouse strains for the small Il17a-expressing T cell Il17 cluster; the T cell CD4 Foxp3 cluster, likely reflecting regulatory T cells; or the CD8 T cell and NK/ILC1 clusters." (PMID 40986319, 2025). "Since the animals in this study were not challenged with M. bovis, we can only speculate that the increased numbers of BCG-specific IFN-γ+ CD4+ T cells in combo vaccinated animals could contribute to enhanced protection against infection." (PMID 40936934, 2025).
infection (continued). "During spreading infection, the cap1G-only virus displayed only minor defects, but the cap3G-only virus showed severe replication delays in both the highly permissive MT-4 cell line and in primary human CD4+ T cells." (PMID 40035516, 2025). "However, after 2 days of infection, we found Dot/Icm-dependent increase numbers of CD4+ and CD8+, neutrophils, and inflammatory monocytes in mice lungs." (PMID 40558085, 2025). "Notably, the IFN‐γ‐producing CD4+ T cell responses were significantly lower following vaccination than after natural infection." (PMID 40820807, 2025). "Notably, while activated effector CD4+ T cells predominantly sustain lytic infection, the direct infection of central and transitional memory CD4+ T cells favors the establishment of latency." (PMID 40650088, 2025). "PT-CY/BEN accelerated CD4+ T-cell recovery, enhanced TCR-β diversity, and preserved early NK-cell numbers, potentially reducing risks associated with delayed immune reconstitution, such as infections and relapse." (PMID 40270968, 2025). "Together, these data show that IL-6 (but not CD4+ cells) contributes to the initial awakening and expansion of dormant DCCs, but that later during the infection, following the recruitment of T cells, CD4+ cells are required for the maintenance of the awakened DCCs." (PMID 40739350, 2025). "Several mechanisms have been described to explain the long-term persistence of HIV reservoirs, including the infection of long-lived CD4+ T cells and clonal expansion by homeostatic or antigen-driven cellular proliferation or by HIV integration in or near genes that promote cellular proliferation." (PMID 41282897, 2025). "This may reflect the stable maintenance of spike-specific CD4 T cell populations through continual antigen exposures via vaccination and infection." (PMID 40251187, 2025). "TLN CD4+ T cells retained GATA‐3 protein expression at d 60 pi, indicating that the loss of GATA‐3 is restricted to the hypo‐responsive phenotype at the infection site." (PMID 40755147, 2025). "Regarding the cellular immune response, CD4 + T-cells have shown to play a protective role by restricting the infection while CD8 + T-cells may contribute to the severity of TBE38." (PMID 40410304, 2025). "CD4+ T cells could possibly secrete soluble factors that enhance HIV-1 macrophage replication or boost productive infection via direct cell-to-cell contact." (PMID 40130873, 2025). "Using our T cell gating strategy, we found that CD4+ and CD8+ T cells were significantly increased in both number and proportion in the lungs of μMT compared with WT mice, during both F/F infection and F/F/S infection, with CD4+ and CD8+ T cells decreased in the lung as a result of MRSA challenge." (PMID 40493422, 2025). "Interestingly, recovery from COVID‐19 does not appear to substantially increase the abundance of iCope‐reactive CD4+ T cells, yet these cells have been shown to be engaged early during infection and vaccination with beneficial effects." (PMID 40726062, 2025). "However, other murine studies have affirmed the protective role of CD4+ T cells in both vaccine-induced and natural infections, showing that depletion of these cells can abrogate vaccine-mediated protection and increase morbidity." (PMID 41295476, 2025). "Finally, mucosal CD4+ T cell losses were similarly massive and swift in both groups, resulting in nearly complete depletion around 28 days after infection (dpi)." (PMID 40662355, 2025). "As early as 6 weeks post-infection, the cysts reactivate when CD4 T cells become exhausted." (PMID 40099884, 2025). "However, the timely control of primary and challenge infection with H. p. bakeri depends on the high number of GATA-3+ CD4+ type 2 T helper cells (Th2) generated in the mesenteric lymph nodes (MLN)." (PMID 39910093, 2025).
infection (continued). "At 5 days post-infection (dpi), significant differences were observed in the numbers of B cells, CD4+ T cells, and CD8+ T cells in the spleens of mice intravenously challenged with either live H1N1 virus or a combination of inactivated E. faecium and inactivated H1N1 virus." (PMID 40909923, 2025). "Altogether, our results demonstrate that CD4 T cells contribute to the enhanced body weight loss early after infection but not viral clearance in OMM12-colonized animals." (PMID 40274773, 2025). "CD4+ T cells assist B cells in making antibodies that induce the macrophages to develop an enhanced microbial activity that recruits neutrophils, eosinophils, and basophils to sites of infection." (PMID 40422863, 2025). "On the contrary, 3BNC117 and 10-1074, which target the GP120 CD4 binding site and the V3 glycan, respectively, showed complete neutralization of CD4+ T cell infection within cocultures for the lab-adapted strain NL4-3 and also inhibited the T cell-mediated enhancement of macrophage infection." (PMID 40130873, 2025). "While CD4+ T lymphocytes have long been recognized as the primary targets of HIV, increasing evidence highlights the susceptibility of myeloid cells, particularly macrophages, to infection, especially through mechanisms involving direct cell-to-cell contact." (PMID 41322423, 2025). "Besides long-standing or—in the case of children—rapidly progressing infection, low CD4 counts and high HIV-1 RNA at initiation were the strongest independent risk factors for BCG-IRIS." (PMID 40559715, 2025). "Additionally, in the spleen, both Ags adjuvanted in GLA-SE plus CDG also increased the Ag-specific CD4+ T cells prior to infection." (PMID 40414893, 2025). "Also, high levels of CD69+ CD4 T-cells persisted until the sixth and seventh months after infection in adult patients." (PMID 41011738, 2025). "Furthermore, children with a subsequent symptomatic infection exhibited significant Th1/Th17 polarization in DENV-specific CD4+ T cells." (PMID 39989460, 2025). "Notably, at 14 dpi, CD8+ αβ T cells displayed a more pronounced infiltration (9-15%) compared with CD4+ αβ T cells (2%–5%) across all infections, highlighting a differential recruitment of effector T cells during pulmonary immune responses." (PMID 40459260, 2025). "However, it has been described that HIV can also polarize CD4+ T lymphocytes toward the Th17 phenotype, thereby inhibiting antiviral elements and ensuring the persistence of the infection." (PMID 41003010, 2025). "However, despite poor in vitro recognition of infected B cells, LANA-specific CD4+ T cells accumulated at the site of infection in vivo." (PMID 41350288, 2025). "Consistently, the RT-qPCR results show that LMP1, IRF4, and PD-L1 were all significantly higher in PBMCs without CD4+ T cells 17 days post-infection, and proliferating colonies were significantly more grown from PBMCs depleted of CD4 T cells compared with intact PBMCs by day 26 post-infection." (PMID 40733503, 2025). "These infections manifest in relation to the severity of CD4+ count suppression." (PMID 40943696, 2025). "However, increased CD4+ T cell turnover is also a double-edged sword, as it gives rise to new target cells that fuel the infection." (PMID 39842407, 2025). "However, the intracellular infection interferes with the early antigen presentation by antigen-presenting cells, thereby retarding the mobilization of activated lung CD4+ T cells (e.g., CD4+ T-memory)." (PMID 41155557, 2025). "In addition, there is a notable influx of CD3+CD4+ T cells into the lungs during the early stages of infection, less than 1% of these cells differentiate into effecter T lymphocytes (Th1, Th17)." (PMID 40607395, 2025). "In summary, KSHV-specific CD4+ T cells accumulating at the site of infection remain early differentiated and maintain CD27 expression, while they might acquire a cytotoxic profile in individual subjects." (PMID 41350288, 2025).
infection (continued). "Thus, Hc-Eng2 was expressed on H. capsulatum yeast during pulmonary infection, and Hc-Eng2–specific CD4+ T cells were induced during infection." (PMID 41061037, 2025). "When comparing the chimeras from T/F versus chronic HIV-1 Env in these NL4–3 backbones, we observed that infection by chimeric T/F HIV-1 was more dependent on higher CD4 levels on the cell surface while able to scavenge for lower CCR5, consistent with previous studies." (PMID 40408432, 2025). "The inflammation triggered by neutrophils may attract other immune cells, including CD4+ T cells, to the site of infection." (PMID 40901106, 2025). "Both gp120s could bind equally well to soluble CD4 and compete with infection of viruses pseudotyped with HIV-1AD8 Envs." (PMID 41201241, 2025). "In particular, identifying polyfunctional CD4+ T cell subsets co-expressing IFN-γ and TNF-α offers promising biomarker candidates to enhance diagnostic specificity, especially for distinguishing between exposure and active infection stages." (PMID 40990013, 2025). "Additionally, the vaccine group had a higher proportion of CD4+ T cells, while the natural infection group had higher levels of CD8+ T cells and natural killer cells." (PMID 40573879, 2025). "Clinically, the CD4/CD8 ratio may be used to indicate infection (if elevated) or compromised immunity (if inverted) although the normal range of 1.5–2.5 is described as poorly defined." (PMID 41261392, 2025). "In summary, while IFNγ and IL‐2 production from bulk T cells, as measured by Fluorospot, was maintained over time post‐infection in the complete cohort, a more detailed examination of S‐specific CD4+ T cells by ICS revealed subset and polyfunctional (3–4 cytokine) responses that declined over time." (PMID 41427434, 2025). "Additionally, CtsD secreted by vaginal epithelial cells enhances HIV transmission by promoting infection of CD4+ T cells and CD4-negative epithelial cells, with its activity influenced by hormones, semen, and the local microbiota." (PMID 41369389, 2025). "This suggests that CD4+ cells may undergo changes in polarization upon arrival at the site of infection." (PMID 41031366, 2025). "Thus, CD4+ T cells are responsible for the majority of MDM recruitment to the lungs during the first 3 weeks of infection." (PMID 40489538, 2025). "As MDV-transformed cells could emerge as early as 10 dpi, the increased CD4+ T cells in this early phase of infection may include transformed cells." (PMID 40673706, 2025). "The reviewed studies highlight the infection of CD4+ T cells and myeloid cells during acute SIV infection, the impact of acute infection on the frequencies and phenotypes of these cells, and the possibility of targeting infected cells in the CNS with drugs that penetrate the BBB." (PMID 40099824, 2025). "The shift in CD4 count during acute mpox infection may result in a significant decrease in the CD4/CD8 ratio, a phenomenon previously observed even in HIV‐negative individuals." (PMID 41204857, 2025). "The MHC−I signaling network revealed elevated activity in T cell:CD4+ effector memory, with significant interactions with NK cell, Neutrophil and Platelets, highlighting their role in driving pro‐inflammatory responses during infection." (PMID 40910395, 2025). "Additionally, the results from our study revealed a significant Th1/Th17 polarization within DENV-specific CD4+ T cells in children who experienced subsequent symptomatic infections." (PMID 39989460, 2025). "Moreover, we found that the CD4 T helper 2 cytokine IL-13 was preferentially induced in the context of infection with modern lineages compared to ancestral lineages (median scaled responses 1.18 [modern] vs. 0.78 [ancestral])." (PMID 40162896, 2025).